SPMIP10 (sperm microtubule inner protein 10)
Description:
Microtubule inner protein (MIP) part of the dynein-decorated doublet microtubules (DMTs) in flagellum axoneme, which is required for flagellum beating. May serve to reinforce and thus stabilize the microtubule structure in the sperm flagella. Involved in the regulation of sperm motility.
Synonyms: C5orf48; TEX43; MGC163367; MGC163369; FLJ27505; Tseg7
Tractability: No criterion of Open Targets' tractability assessment is met for any kind of drug.
Gene: Protein-coding gene on chromosome 5 (126,631,705 to 126,636,284, forward strand). Ensembl gene ENSG00000196900.
Subcellular location: Cytoplasm, cytoskeleton, flagellum axoneme
Subcellular location (Human Protein Atlas): Mid piece
Gene Ontology:
Molecular function: protein binding
Biological process: flagellated sperm motility
Cellular component: axonemal B tubule inner sheath; sperm flagellum
Genetic constraint (gnomAD): Loss-of-function variants: 4 observed, 5.71 expected, observed/expected ratio (o/e) 0.7, 90% interval 0.34 to 1.55. That is too few expected variants to judge how well the gene tolerates losing a copy. Missense variants: 76 observed, 85.49 expected, observed/expected ratio (o/e) 0.89, 90% interval 0.74 to 1.08. Synonymous variants: 33 observed, 31.17 expected, observed/expected ratio (o/e) 1.06, 90% interval 0.8 to 1.41.
Homologues: Orthologues: chimpanzee SPMIP10 (100% identical), macaque SPMIP10 (93% identical), dog SPMIP10 (87% identical), pig SPMIP10 (83% identical), rabbit SPMIP10 (83% identical), guinea pig SPMIP10 (82% identical), rat Spmip10 (77% identical), mouse Spmip10 (75% identical).